PINK1 (PTEN induced kinase 1)
Diseases named in the same sentence as PINK1 in open-access papers (continued):
Sharing a sentence is not in itself a finding about the gene and the disease.
Parkinson disease (continued). "Rabin8 activation of the Rab8 GTPase (the human homologue of yeast Sec4p) is blocked by PTEN-induced kinase 1 (PINK1), an autosomal recessive agent of Parkinson’s disease, suggesting a link between Parkinson’s disease and Rab8 activation by Rabin8." (PMID 39560727, 2024). "In addition, Miro GTPases have been implicated in Parkinson’s disease—and possibly other neuropathological conditions—based on their interactions with the Parkinson protein Parkin, which is an E3 ubiquitin ligase, and the PTEN-induced kinase (PINK1), which is a Ser/Thr protein kinase." (PMID 38607086, 2024). "For example: In Parkinson’s disease, lncRNA NEAT1 increases stabilization of PTEN-induced putative kinase 1 (PINK1), hence promoting cellular quality control mechanism." (PMID 35359568, 2022). "Well-established Parkinson’s disease genes include autosomal dominant forms (SNCA, LRRK2, and VPS35) and autosomal recessive forms (PRKN, PINK1 and DJ1)." (PMID 35328025, 2022). "Owing to mitochondrial depolarization stabilizing PINK1, both PINK1 and PARKIN are recruited to damaged mitochondria, and latent PARKIN is activated for mitophagy in Parkinson’s disease." (PMID 34967891, 2022). "For example, collectively, genetic models like Pink1, SLC18A2, Ndufs4, ASO as well as neurotoxin models such as 6-OHDA cover the range of Parkinson disease signs." (PMID 33928251, 2021). "The importance of PINK1 (PTEN-induced putative kinase 1) and Parkin for mitochondrial homeostasis is supported by the accumulation of dysfunctional mitochondria in Parkinson’s disease (PD) models and patients." (PMID 33782711, 2021). "Related to the occult formation of autophagosomes, PINK1 (PTEN-induced putative kinase 1) and Parkin have been research hotspots in the field of Parkinson's disease in recent years." (PMID 33981351, 2021). "The serine/threonine kinase phosphatase and tensin homolog (PTEN)-induced putative kinase 1(PINK1) controls mitochondrial quality and plays a vital role in the pathogenesis of early-onset Parkinson's disease." (PMID 31139191, 2019). "Indeed, mutation of either the genes encoding the PINK1 and Parkin proteins (PINK1 and PRKN, respectively) can result in the accumulation of dysfunctional mitochondria in animal and cell models and is associated with juvenile onset autosomal recessive forms of Parkinson’s disease (PD;)." (PMID 31412778, 2019). "In this study, we expect to generate human Parkinson’s disease pig model using CRISPR/Cas9 system by simultaneously targeting three distinct genomic loci, parkin/DJ-1/PINK1, in Bama miniature pigs." (PMID 26857844, 2016). "It is a component of Lewy bodies in Parkinson's disease brains and a reduction of phospho-NFM levels was already observed in PINK1-KO mouse brains." (PMID 27034888, 2016). "Interestingly, flies lacking the homologues of Parkinson’s disease susceptibility genes PTEN-induced putative kinase 1 (Pink1) or parkin, which modulate mitochondrial dynamics and function, also display motor defects that are most severe in indirect flight muscle." (PMID 26599788, 2015). "Using Drosophila as an example, this species has single orthologs for Parkinson disease-related genes PINK1 and PARK2, and has been used to study the mitochondria-related pathomechanisms in Parkinsonism." (PMID 26230726, 2015). "The characterization of the interaction between PINK1 and BAG5 under physiological status or pathological state will lead to an improved understanding of the pathogenesis of Parkinson's disease and, ultimately, possibly to novel therapeutic approaches." (PMID 24475098, 2014). "More analysis of the functional interaction between PGAM5 and PINK1 would reveal the role for PGAM5 in the mitochondrial quality control and possibly in the pathogenesis of Parkinson’s disease." (PMID 23443160, 2013).
Parkinson disease (continued). "While PINK1 knock-out mice display no significant phenotype, Drosophila PINK1 null flies exhibit a striking phenotype sharing many overlapping behavioural and cellular features with human Parkinson's disease, including motor deficits, neuronal loss and mitochondrial abnormalities." (PMID 22645651, 2011). "It is clear, therefore, that PINK1 may play a rather central physiological role in neuronal and myocyte energy metabolism, consistent with its abundant expression in mitochondria-rich tissue and consistent with the proposed mitochondrial basis for Parkinsonism." (PMID 17362513, 2007). "The role of Drp1 has been identified as a contributing factor in the pathogenesis of Parkinson’s disease, with a substantial body of evidence demonstrating the involvement of α-Syn, DJ-1, LRRK2, PINK1, and Parkin in the regulation of mitochondrial dynamics and homeostasis through the Drp1 pathway." (PMID 40463912, 2025). "QC25 alleviates oxidative stress, restores energy metabolism, and stabilizes mitochondrial membrane integrity in Parkinson’s disease models, while its bioactive component 6-gingerol synergizes with plant-derived L-DOPA to enhance mitophagy via PINK1/Parkin pathway activation." (PMID 41008216, 2025). "Several pathological mutations in the genes coding for PTEN-induced Kinase 1 (PINK1), Parkin, Leucine Rich Repeat Kinase 2 (LRRK2), glucocerebrosidase 1 (GBA1) and DJ-1 or PARK7 (Parkinson disease protein 7) were subsequently reported and established the genetic link to PD." (PMID 40540721, 2025). "In Parkinson’s disease, autophagy activation via agents such as metformin has shown neuroprotective effects by activating the AMPK/ULK1/PINK1/Parkin pathway, thereby enhancing autophagy and mitophagy, promoting mitochondrial clearance, and reducing neuronal apoptosis in experimental models." (PMID 41007413, 2025). "We have separated these into 4 categories, namely diseases (e.g., Parkinson’s, Alzheimer’s), enzymes (e.g., kinases, phosphatases), organelles (e.g., Golgi, lysosomes), and pathways (e.g., LRRK2, PINK1), that are listed in Dataset S2, and these can readily be updated and added to." (PMID 38324566, 2024). "The first described and therefore most characterised mitophagy pathway is composed of the two key proteins, PINK1 (phosphatase and tensin homolog (PTEN)-induced putative kinase 1) and Parkin, which have been identified in Parkinson’s disease, the second most common neurodegenerative disease." (PMID 37410705, 2023). "In Parkinson’s disease models, suppressed mitochondrial PTEN-induced kinase 1 (PINK1) is proposed to contribute to, if not underpin, MHC-1 upregulation, coupled to a decrease in mitophagy and associated metabolic dysregulation." (PMID 36834709, 2023). "Through the pink-1(PTEN-induced putative kinase 1)/pdr-1 (ortholog of PARKIN in mammalians, Parkinson’s disease-related 1) protein pathway, the pink-1 protein is recruited to the outer membrane of the mitochondria, phosphorylating both ubiquitin and the Parkin protein, and activating the latter." (PMID 37372124, 2023). "Recent data showed intestinal Gram-negative bacteria infection to trigger Parkinson’s disease-like symptoms in PINK1 ko mice, which can be successfully treated with L-DOPA." (PMID 37174637, 2023). "For example, flies lacking parkin or Pink1 function show significant cellular toxicity and mitochondrial dynamics defects relevant to those seen Parkinson’s disease patients, while even aged triple parkin/PINK1/DJ-1 mice do not show clear neurodegeneration." (PMID 37923712, 2023). "The PINK1/Parkin mitophagy pathway, as well as alternative mitophagy pathways controlled by BNIP3L/Nix and FUNDC1, are emerging targets to enhance mitophagy to treat Parkinson's disease." (PMID 35311891, 2022).
Parkinson disease (continued). "Although recent studies have demonstrated that irregulating PINK1 expression can improve Parkinson’s disease and pulmonary fibrosis, the role of mitophagy in RA had not previously been investigated." (PMID 35628458, 2022). "Loss of function of PTEN-induced putative kinase 1 (PINK1) failed to recruit Parkin to mitochondria, which was reported as a cause of mitochondrial autophagy dysfunction and parkinsonism in humans." (PMID 36552538, 2022). "Therefore, the authors hypothesize that parkin and PINK1 prevent inflammation and neurodegeneration by clearing damaged mitochondria, thereby preventing increases in cytosolic and circulating mtDNA, suggesting a new model for how mitophagy may mitigate Parkinson’s disease." (PMID 35453534, 2022). "Below, we describe the usefulness of the Pink1−/− rat model in studying early-onset Parkinson disease, non-limb motor clinical signs, and pathology outside of the classical nigrostriatal dopamine loss." (PMID 33928251, 2021). "We found similar phenotypes in mice lacking PTEN-induced kinase 1 (PINK1), mutations in which cause recessive familial Parkinson’s disease." (PMID 33805219, 2021). "A similar phenomenon has been observed in a mouse model of a Mendelian form of Parkinson’s: Pink1 knockout mice did not develop Parkinson’s symptoms unless inoculated with Gram-negative bacteria." (PMID 33972690, 2021). "No genetic model of Parkinson disease is perfect, but the Pink1−/− rat model is appropriate, for answering certain research questions." (PMID 33928251, 2021). "As such, we do not want to diminish the value of the Pink1−/− model when there are robust deficits and mechanisms that parallel human Parkinson disease that are represented in this model, albeit sometimes imperfectly." (PMID 33928251, 2021). "Further investigation found that stabilization of PINK1 by BAG2 triggers Parkin-mediated mitophagy and protects neurons against 1-methyl-4-phenylpyridinium-induced oxidative stress in an in vitro cell model of Parkinson’s disease." (PMID 28536620, 2016). "HtrA2 functionally interacts with the mitochondrial protein kinase PINK1 and mouse models lacking HtrA2 develop neurological defects reminiscent of Parkinson's Disease." (PMID 26977249, 2016). "However, mutations in several genes have been shown to result in clinically typical autosomal dominant (SNCA, LRRK2, VPS35, DNAJC13) or recessive (PARK2, PINK1, PARK7) PD, or parkinsonism with atypical features (e.g. PARK9)." (PMID 26399558, 2015). "In addition, previous studies showed that mice with mutations in PINK1 or parkin, as opposed to those in humans and flies, display subtle signs of Parkinson's disease: the fact that these are weak suggests that other unknown proteins or cellular pathways might compensate for loss of the genes." (PMID 24898855, 2014). "The most important and widely accepted monogenically inherited Parkinson's disease genes are α-synuclein (SNCA) and leucine-rich repeat kinase 2 (LRRK2) for late-onset disease and Parkin (PARK2), oncogene DJ1 (DJ1) and PTEN Induced Putative Kinase 1 (PINK1) for early onset." (PMID 24133413, 2013). "In particular for monogenic forms of disease, patient-derived iPSCs have already been shown to recapitulate known disease mechanisms, as shown in spinal muscular atrophy, fragile X syndrome, progeria syndrome, and several genetic forms of Parkinson disease (PD) like LRRK2, PINK1, SNCA, and GBA." (PMID 22567022, 2012). "Mutations in PARK7 can cause autosomal recessive parkinsonism, and the clinical presentation of the early onset and slow progression of this form of parkinsonism is similar to that of the other recessive PD syndromes such as PARK2 (parkin) and PARK6 (PTEN-induced kinase 1, PINK1)." (PMID 22132160, 2011).
Parkinson disease (continued). "There is reliable evidence for this in mice modeling Parkinson’s disease: Pink1–/– or Prkn–/– mice display a strong STING-dependent neuroinflammatory and innate immunity signature that can be alleviated by restoration of the abundance of either Pink1 or Parkin." (PMID 39156128, 2024). "This increase is mediated by the protein ULK1, suggesting that the process may be independent of PRKN,128 despite higher activation of “PINK1 accumulation” in the simulation for the parkinsonism cohort." (PMID 39429779, 2024). "Leading examples include Parkin RBR E3 Ubiquitin Protein Ligase (PRKN), PTEN-induced kinase 1 (PINK1) and Parkinson disease protein 7 (PARK7), with robust evidence linking them to the development of PD." (PMID 39456761, 2024). "In addition, phosphorylation of NCLX by protein kinase A (PKA) has been found to enhance its ability to facilitate the efflux of mCa2+, effectively preventing the degeneration of neurons lacking PINK1, a cellular model of Parkinson’s disease (PD)." (PMID 37601094, 2023). "Mice that lack either PINK1 or Parkin do not display parkinsonism-related phenotypes." (PMID 33537300, 2020). "However, we are cognizant that neither Parkin nor PINK1 null mice exhibit robust signs of Parkinsonism despite showing selective disruption of AMPK-PGC-1α axis in their ventral midbrain." (PMID 30411223, 2019). "Moreover, mice lacking PINK1 have typical symptoms of Parkinson’s disease including mitochondrial impairment of dopaminergic neurons." (PMID 23348931, 2013). "Also, alpha-synuclein, Leucine-rich repeat kinase 2, ubiquitin carboxyl-terminal hydrolase L1, Parkin, Pink1, Grb10-Interacting GYF Protein-2, or Omi/HtrA2, which are implicated in Parkinson's disease, are not included." (PMID 21731734, 2011). "The lentiviral approach used in the present study could similarly be used to examine the effects of aging on the toxicity of mutant proteins involved in other neurodegenerative diseases (e.g. PS1/APP for Alzheimer's disease, and DJ-1, PINK-1, and LRRK2 for Parkinson's disease)." (PMID 19247483, 2009). "However, it is important to note that although PINK1 KO MEFs provide valuable insight into cellular mechanisms related to PINK1 and certain aspects of Parkinson’s disease, their use alone might not fully capture the complexity of the disease." (PMID 38203389, 2023). "The PINK1-dependent subtle molecular mismanagement of variably reoccurring life events such as infections (in our data mimicked by polyI:C) or hunger (mimicked by HBSS medium) may determine, if the clinical manifestation of Parkinson’s disease occurs early or late in life." (PMID 28768533, 2017). "Some nuclear mitochondrial genes have a role in common diseases like Parkinson’s disease, where a defect in the PTEN-induced kinase 1 (PINK1) or in the E3 ubiquitin ligase, Parkin, lead to a lack of mitochondrial quality control." (PMID 32485941, 2020).
Parkinsonism (140 papers, 2005 to 2026). Characteristic neurologic anomaly resulting from degeneration of dopamine-generating cells in the substantia nigra, a region of the midbrain, characterized clinically by shaking, rigidity, slowness of movement and difficulty with walking and gait. "Although most PD cases are sporadic, mutations in parkin (PARK2), DJ-1 (PARK7) and PINK1 (PARK6) have been linked to recessively inherited forms of parkinsonism." (PMID 22792356, 2012). "Furthermore, single heterozygous PARK2 or PINK1 variants are higher in PD patients than controls and have been associated with subclinical parkinsonism." (PMID 35893043, 2022). "Direct interactions between genetic components and these pathways are emerging, whether VPS35 and RME-8 in late onset PD, or parkin and PINK1 in mitophagy in early onset parkinsonism." (PMID 25061481, 2014). "In addition to pathogenic mutations in well-established PD-related genes (LRRK2, PRKN, PINK1, SNCA, PLA2G6 and GBA1), we identified pathogenic mutations in genes that have been reported to present as levodopa-responsive parkinsonism but typically present with alternative or atypical phenotypes." (PMID 39420034, 2024). "In particular, we envisage that more detailed investigations on experimental models of GBA1-, SYNJ1-, SYPH1-, TMEM230-, Parkin-, PINK1-, ATP13A2-, FBXO7- and SYT11-associated parkinsonism could provide new insight into the pathophysiological mechanisms leading to PD that may involve Rab dysfunction." (PMID 36009486, 2022). "Interestingly, several PD-associated genes such as Pink1, Parkin, and Synj1, associated with early onset parkinsonism without robust evidence of synucleinopathy, did not impact synuclein aggregation in this screening assay." (PMID 30927072, 2019). "Mutations in seven genes were robustly associated with autosomal dominant (SNCA, LRRK2, EIF4G1, VPS35) or recessive (parkin/PARK2, PINK1, DJ1/PARK7) PD or parkinsonism." (PMID 29881367, 2018). "For instance, several PD genes, such as parkin, DJ-1, Pten induced kinase 1 (PINK1), or ATP13A2, contribute to early onset autosomal recessive forms of Parkinsonism." (PMID 25426138, 2014).